HLA-G (major histocompatibility complex, class I, G)
Diseases named in the same sentence as HLA-G in open-access papers (continued):
Sharing a sentence is not in itself a finding about the gene and the disease.
tumor (continued). "Moreover, the fact that HLA-G expression status can dramatically affect therapeutic responses has been addressed in tumor patients and patients with other diseases." (PMID 30319626, 2018). "Additionally, hypoxia during the development of glioma activates HLA-G, an immune checkpoint molecule that contributes to the immune escape of tumor cells." (PMID 30619286, 2018). "Therefore it is highly unlikely that strong adaptive anti-tumor immune responses preexist in this cancer which are inhibited by HLA-G and/or other immune-inhibitory mechanisms and just need to be unleashed to reject the cancer." (PMID 29464090, 2018). "Given the immune suppressive functions of HLA-G in favoring tumor immune evasion and progression, induction of HLA-G expression during immune therapy which may impair the therapeutic effects, should be considered." (PMID 30319626, 2018). "On the other hand, soluble HLA-G secreted by both tumor and immune cells may directly inhibit CD4+ and CD8+ T cell proliferation." (PMID 30574154, 2018). "Besides application of the clinical tumor lesions, the direct roles of HLA-G participating in cancer progression have been demonstrated in previous studies with murine models." (PMID 30234020, 2018). "In a mouse model, HLA-G alone was able to prevent tumor immune rejection." (PMID 29464090, 2018). "Paraffin-embedded pretherapeutic tumor biopsies from 49 pediatric and young adult patients with newly diagnosed (n = 47) and/or relapsed (n = 12) EwS were analyzed by immunohistochemistry using the HLA-G specific antibody clone 4H84." (PMID 29464090, 2018). "In addition, HLA-G itself can generate at least seven distinct isoforms, and intertumor and intratumor heterogeneity of HLA-G expression is common across different tumor types." (PMID 30319626, 2018). "In vitro, HLA-G expression even in a minor subpopulation of tumor cells was sufficient to provide bystander protection of HLA-Gneg cells, though by unknown mechanisms." (PMID 29464090, 2018). "The observation that HLA-G was expressed at both of two tumor sites in one patient supports uniformity of this feature but remains anecdotal and is difficult to reproduce since routine diagnostic procedures do not stipulate pretherapeutic biopsies from more than one site." (PMID 29464090, 2018). "We hypothesized that HLA-G expression in EwS is a consequence of an inflammatory immune response in the local tumor microenvironment." (PMID 29464090, 2018). "Substantial previous evidence has proved that HLA-G is a crucial tumor-driven immune escape factor involved in alterating the anti-tumor responses of immune contexture of solid tumors like CRC, and thus in determination of the fate of tumor development and patient clinical outcome." (PMID 30234020, 2018). "Through binding to the immune inhibitory receptors (particularly ILT2 and/or ILT4) expressed on various immune cells, HLA-G could directly or indirectly impair anti-tumor immune responses." (PMID 30234020, 2018). "Although the degradation of surface HLA-G may stimulate an antitumor immune response, at the same time numerous cancer immune evasion mechanisms occur in the tumor microenvironment." (PMID 29467963, 2018). "However, the degree of HLA-G expression also varies dramatically among different laboratories for almost every histological type of tumor studied." (PMID 30319626, 2018). "The key question is whether HLA-G expression in EwS is relevant to protect the tumor from natural and therapeutic immune responses." (PMID 29464090, 2018). "Since HLA-G is considered an immune checkpoint molecule, augmentation of HLA-G expression in hypoxic tumor cells may contribute to immunosuppression in tumors." (PMID 30061885, 2018). "Thus, APCs expressing HLA-G in the tumor microenvironment have suppressive properties and are partly responsible for tumor immune escape." (PMID 30574154, 2018).
tumor (continued). "HLA-G molecules can be transferred from tumor cells to activated NK cells and other immune cells by a process called trogocytosis, which involves the delivery of plasma membrane fragments from one cell to another leading to downregulation of the immune response." (PMID 30574154, 2018). "Otherwise, it is possible that HLA-G+ tumor cells may adapt to hypoxia directing the cell energy in productive gene expression at the expense of HLA-G, however maintaining the protection against host immune defenses carried by surface HLA-G expression." (PMID 28781970, 2017). "Thus, in hematological diseases, the role of HLA-G is more complex than in solid tumors and depends on the balance between inhibition of anti-tumor responses and the anti-proliferative effects on malignant B cells." (PMID 29285306, 2017). "Overall, these observations support the hypothesis that a HLA-G posttranscriptional regulation is present and may involve phenotypic in vivo factors present in the tumor microenvironment, especially when inflammatory processes are active." (PMID 28781970, 2017). "Indeed, the immune checkpoint molecule HLA-G contributes to the mechanisms used by tumor cells to differentiate towards cells with reduced immunogenicity." (PMID 28781970, 2017). "Thus, influence of hypoxia on modulation of HLA-G, which is a physiologically relevant tumor-related stress gene, was investigated." (PMID 28781970, 2017). "The definition of these nucleotide regions could in part explain the different responses on HLA-G expression under hypoxia conditions observed among the tumor cell lines and TCGA cohorts, thus evidencing novel possible treatment strategies." (PMID 28781970, 2017). "Altogether, these results are consistent with the existence of a novel HLA‐G transcript, named HLA‐G1L, having an extended 5′‐end, which might be coexpressed in trophoblasts and ccRCC tumor cells with previously reported HLA‐G isoforms." (PMID 28815885, 2017). "The two overexpression miRNAs in ccRCC cell line caused a downregulation of HLA-G gene and protein and mir-548q could be able to revert to the immune escape of HLA-G expression tumor cells." (PMID 29299153, 2017). "However, HLA-G expression would be detrimental in solid tumors and virally infected cells, where it suppresses immune response by inhibiting NK cells that kill tumor cells." (PMID 29285306, 2017). "In addition to the tumor lesion HLA-G expression was intensively investigated; however, the value of peripheral sHLA-G in prognosis is very limited but now emerging." (PMID 28415627, 2017). "Immunohistochemical analysis of HLA-G expression in tumor cells from 25 lymph node biopsies that were obtained at diagnosis showed that patients carrying a +3027 C/A genotype were all negative for HLA-G and only 5 cases having the wild type +3027 C/C genotype showed HLA-G expression (20%)." (PMID 29285306, 2017). "In addition, high levels of HLA-G in HCV and hepatocellular carcinoma are associated with shortened overall survival and increased tumor recurrence rate." (PMID 28769934, 2017). "Moreover, since the HLA-G +3027-A variant was found associated with lower HLA-G expression, our data might suggest that patients with the +3027-C/A genotype are more prone to tumor relapse because more prone to decreased expression in HLA-G, which affects HL tumor cell apoptosis." (PMID 29285306, 2017). "Previously, HLA-G expression was reported in adult HL patients belonging to Ann Arbor stages IIb-IV in the tumor microenvironment in patients showing positron emission tomography (PET)-positive (carried out after 2 cycles of standard chemotherapy) during follow-up." (PMID 29285306, 2017). "Interestingly, it was possible to inhibit the development of the tumor in vivo with the administration of a specific anti-HLA-G blocking antibody." (PMID 27999823, 2016). "The microenvironment of the tumor or the transformed cells per se may induce HLA-G expression, impairing the activity of NK cells." (PMID 27517300, 2016).
tumor (continued). "In addition, high levels of soluble HLA-G in sera and ascites of tumor patients were correlated with an advanced disease status and higher tumor load." (PMID 27057628, 2016). "Indeed, cytotrophoblast cells, mesenchymal stem cells, and cancer cells were recently described to secrete HLA-G-bearing EVs, displaying immunosuppressive effects and modulating the tumor microenvironment." (PMID 27199995, 2016). "However, these authors found that only HLA-G expression can serve as independent factor for OS, whereas the expression of HLA-E was significantly correlated with tumor metastasis." (PMID 27652273, 2016). "In such a situation, resident hypoxia and DNA demethylation acting both at the HLA-G promoter region and HRE sites, might provide favorable conditions for ectopic HLA-G expression and then tumor invasion." (PMID 27577073, 2016). "Hypoxia occurs during placenta and tumor development and was shown to activate HLA-G." (PMID 27577073, 2016). "Moreover, they demonstrated that HLA-G levels represented an independent predictor for patients' OS, and a positive correlation was found between HLA-G expression and tumor stage, extrapancreatic infiltration, lymph node involvement, and poor differentiation." (PMID 27652273, 2016). "Finally, tumor tissue samples tested positive for HLA-G and LILRB1 protein expression, and those expression levels significantly correlated with tumor stage." (PMID 27652273, 2016). "Interestingly, for miR-628-5p a tumor-suppressive function has been described as it has been also shown for other HLA-G regulatory miRs e.g. miR-148a, -148b, -152 and miR-133a." (PMID 27057628, 2016). "Apart from pregnancy, HLA-G has been shown to be expressed in many types of tumours." (PMID 26862036, 2016). "Human leukocyte antigen (HLA)-G acts as negative regulator of the immune responses and its expression may enable tumor cells to escape immunosurveillance." (PMID 27517300, 2016). "In addition, HLA-G molecules can be transferred by trogocytosis to competent cytotoxic cells rendering them unresponsive to tumor antigens." (PMID 27517300, 2016). "Next to this it was investigated whether a correlation between HLA-E expression in RCC lesions and WHO tumor grading exists, which was statistically significant for HLA-G as recently reported." (PMID 27589686, 2016). "Interestingly, hβ2m+ HLA-G5− tumors were rejected, whereas hβ2m+ HLA-G5+ tumors secreted soluble HLA-G, which protected them from hβ2m-elicited immune rejection, and grew similarly to a poorly immunogenic tumor." (PMID 27652273, 2016). "Although the study of HLA-G expression in tumor cells has been widely explored [reviewed at Ref." (PMID 25699038, 2015). "Th2 versus Th1/Th17 constitute the main mechanisms by which HLA-G promotes tumor expansion." (PMID 26460949, 2015). "Indeed, immunohistochemistry analyses of tumor biopsies and serology have demonstrated that investigating the expression of HLA-G is relevant for determining the prognosis of solid cancers." (PMID 26460949, 2015). "In the scenario of malignancies, ectopic induction of HLA-G expression has been observed in various types of tumours including haematological and solid tumours, where different sources of HLA-G expression exist such as on the cell surface, secreted or incorporated into tumour-derived exosomes 7–9." (PMID 25689063, 2015). "Considering that the non-classical HLA-G molecule has well-recognized tolerogenic properties, HLA-G expression is expected to be deleterious when present in tumor cells and in cells chronically infected by viruses, whereas HLA-G expression is expected to be advantageous in autoimmune disorders." (PMID 25699038, 2015). "Finally, we found that NK-10 cells have an improved proliferative response to HLA-G expressing tumor cells (p < 0.01)." (PMID 26460949, 2015). "HLA-G+ tumor lines were routinely checked for the expression of HLA-G." (PMID 26460949, 2015).
tumor (continued). "Analysis of cross-talk between tumor B cells, HLA-G+ mesenchymal stem cells, and osteoblasts in bone marrow may provide insights in understanding the mechanisms of tumor suppression in vivo in this biological compartment." (PMID 24800261, 2014). "HLA-G and -E can also co-operate in the tumor microenvironment to induce local anergy." (PMID 25202308, 2014). "Five-year survival of patients with tumours expressing HLA-G was significantly better (P = 0.001)." (PMID 24987709, 2014). "This could help to induce HLA-G in a tissue when a suppressive action is convenient (e.g., organ transplantation) or to suppress it when its expression is harmful (e.g., tumor)." (PMID 24818168, 2014). "Furthermore, our analyses showed that HLA-G expression in these tumours is correlated with residual disease after surgery and sensitivity to platinum chemotherapy." (PMID 24987709, 2014). "In this context, expression of the tolerogenic HLA-G molecule represents a mechanism that may favor tumor survival through interaction with inhibitory receptors." (PMID 24800261, 2014). "Also, in this case, however, an opposite role of HLA-G and -E in tumor progression was demonstrated." (PMID 25202308, 2014). "The median level of HLA-G gene expression in tumour tissue was 230.38 fluorescence units." (PMID 24987709, 2014). "Both PFS and DSS were significantly better when tumours expressed HLA-G." (PMID 24987709, 2014). "In addition, activated NK cells acquired HLA-G, an immunosuppressive molecule, from tumor cells via trogocytosis, leading to impaired cytotoxicity." (PMID 25313995, 2014). "The HLA-G gene might be responsible for the inhibition of T and NK cells, facilitating tumor escape from immune surveillance." (PMID 24870375, 2014). "Our data provide evidence that HLA-G may inhibit tumor cell proliferation through mTOR signaling blockade." (PMID 24800261, 2014). "In addition, HLA-G expression was induced in several tumor cell lines by using demethylation agents, such as 5-aza-2′deoxycytidine." (PMID 24741620, 2014). "In contrast with these studies, several groups have demonstrated that HLA-G and -E may have different or even opposite roles in tumor progression." (PMID 25202308, 2014). "HLA-G induces suppressive NK cells through trogocytic acquisition of HLA-G from tumor to NK cells." (PMID 25187842, 2014). "One might either stop HLA-G transcription or interfere with its surface expression or secretion or block direct interaction between HLA-G expressed by tumor cells and inhibitory ILT receptors present on immune cells." (PMID 24800261, 2014). "HLA-G can be found on tumor cells as well as on tumor-infiltrating cells." (PMID 24800261, 2014). "These pro-inflammatory cytokines may be involved in HLA-G up-regulation, and HLA-G may allow infected cells or tumor cells to escape immune responses." (PMID 23418570, 2013). "HLA-G and HLA-E expression at the tumor cell surface might allow it to escape T and natural killer (NK) cell immune surveillance." (PMID 24363939, 2013). "Furthermore, HLA-G is often expressed in solid and hematologic tumors either as a transmembrane and/or a secreted/shed protein, thereby protecting tumor cells from the cytolytic activity of natural killer (NK) and T cells." (PMID 24348482, 2013). "We explored the occurrence of spontaneous de-methylation in the HLA-G promoter as a surrogate of re-expression of the HLA-G protein in HPV-infected cells, as the HLA-G protein is a recognized inducer of a tolerogenic effect and tumor escape from immunosurveillance." (PMID 23265140, 2012). "Among them, calprotectin, a potent inflammatory protein, and HLA-G, endowed with tolerogenic properties facilitating tumor escape from host immune response, may represent novel biomarkers and/or targets for therapeutic intervention in high-risk NB patients." (PMID 22253825, 2012). "Therefore, the distribution of HLA-G is mostly limited to foetal trophoblastic tissues and numerous tumour tissues." (PMID 23002136, 2012).
tumor (continued). "Assuming that HLA-G gene silencing depends on a flexible, DNA structure-based mechanism, we speculate that HLA-G expression may be activated in the foetal placenta or in some tumours via positive regulation." (PMID 23002136, 2012). "For example, there is evidence that HLA-G can be transferred from a tumour cell to a healthy cell, conferring the same NK cell suppression function that it had on the tumour cell and T-cells that acquired CD80 and HLA-DR from antigen presenting cells developed an antigen presenting-cell function." (PMID 20046883, 2009). "For instance, epigenetic cancer therapies using DNA methylation inhibitors to prevent inactivation of classical HLA may in turn activate expression of HLA-G and thus could favour tumour immune escape." (PMID 18397301, 2008). "Although the highest levels of HLA-G expression were associated with tumor samples, no significant overall correlation between methylation and expression levels was detected by real time RT-PCR." (PMID 18498645, 2008). "Moreover, HLA-G expressions may be modulated by inflammatory cytokines, such as interferon-γ, further shaping the immunosuppressive tumor microenvironment." (PMID 42083155, 2026). "According to this study, blockade of KIR2DL4/HLA-G signaling using specific antibodies or other immunomodulatory agents, might be possible to enhance the antitumor activity of immune cells and improve the efficacy of tumor immunotherapy." (PMID 40549069, 2025). "HLA-G is a non-classical HLA class I antigen that induces immune suppression and is closely associated with poor prognosis, making it a promising non-self- and tumor-site-agnostic target for immunotherapy." (PMID 41194925, 2025). "The poor prognosis in cluster 1 was associated with a less immunogenic tumor microenvironment, characterized by lower TME scores, increased infiltration of immunosuppressive M0 macrophages, and downregulation of key antigen-presenting molecules including HLA-G." (PMID 40777020, 2025). "The results of this study showed that with the progression and malignant transformation of sinonasal inverted papilloma, the expression of HLA-G increased and was significantly correlated with tumor grade, suggesting that it may be involved in the progression of SNIP-SCC." (PMID 38427106, 2024). "Notably, HLA-G is increased in MIBC with an immune evasive microenvironment (high PD-L1 tumor cell expression, NK cell depletion, granzyme B (GZMB)/CD8 ratio reduction, MHC class I (MHCI) expression reduction) that are characterized by immunosuppressive features and poor prognosis." (PMID 39469714, 2024). "Moreover, glycosylated HLA-G was produced by placental trophoblast cells and secreted into the amniotic fluid, being crucial for the maintenance of maternal–fetal immune tolerance, but mechanistic evidence for the role of HLA-G in tumor immune-evasive is still missing." (PMID 38310272, 2024). "However, expression of HLA-G and PD-L1 was upregulated concomitantly, reshaping the suppressive tumor immune microenvironment, which might be a contributor to the poor efficacy of such drugs." (PMID 38310272, 2024). "In addition to this, ablation of HLA-G using RNAi or CRISPR/Cas9 gene editing may also potentiate the anti-tumor response." (PMID 38310272, 2024). "Targeting HLA-G or its receptors may enhance anti-tumor immune responses." (PMID 39040441, 2024). "Additionally, the ability to quantify soluble HLA-G in the blood, its predictive value when co-expressed with other immune checkpoints, and its consistent presence across various tumor regions further highlight its utility as a potential biomarker and therapeutic target." (PMID 39469714, 2024). "In addition to avoid from activating NK receptors, tumor cells can upregulate the expression of inhibitory ligands, such as HLA‐G (ligand for KIR), HLA‐E (ligand for NKG2A/CD94), or PD‐L1, which engage inhibitory receptors on NK cells, resulting in the inhibition of NK cell cytotoxicity." (PMID 38882209, 2024).